ARSH (arylsulfatase family member H)
Synonyms: sulfatase
Tractability: Antibody: UniProt predicts a signal peptide or a membrane-spanning region.
Gene: Protein-coding gene on chromosome X (3,006,546 to 3,034,111, forward strand). Ensembl gene ENSG00000205667.
Subcellular location: Membrane
Pathways (Reactome):
Metabolism: Glycosphingolipid catabolism
Metabolism of proteins: The activation of arylsulfatases
Gene Ontology:
Molecular function: arylsulfatase activity
Cellular component: endoplasmic reticulum lumen; membrane
Homologues: Orthologues: macaque ARSH (97% identical), dog ARSH (89% identical), chimpanzee ARSH (77% identical), Drosophila melanogaster CG7408 (25% identical), Caenorhabditis elegans sul-2 (25% identical), Drosophila melanogaster CG32191 (25% identical), Drosophila melanogaster CG7402 (24% identical), zebrafish arsib (24% identical), Caenorhabditis elegans sul-3 (21% identical), Drosophila melanogaster Sulf1 (19% identical), zebrafish sulf2a (19% identical), Caenorhabditis elegans sul-1 (18% identical), and 2 more. Paralogues in human: ARSD (64% identical), ARSL (60% identical), ARSF (59% identical), STS (52% identical), GALNS (30% identical), ARSG (29% identical), ARSA (29% identical), ARSI (25% identical), ARSB (23% identical), SGSH (22% identical), ARSJ (22% identical), SULF2 (21% identical), and 4 more.
Diseases named in the same sentence as ARSH in open-access papers:
ARSH is named in the same sentence as 4 diseases in open-access papers, as found by Europe PMC text mining. Sharing a sentence is not in itself a finding about the gene and the disease.
ARSH shares sentences with these, for which no sentence is quoted: colorectal cancer (1 paper); genetic disorders (1); Roifman syndrome (1); tumor (1).